FOXK1 (forkhead box K1)
Diseases named in the same sentence as FOXK1 in open-access papers (continued):
Sharing a sentence is not in itself a finding about the gene and the disease.
ovarian carcinoma (13 papers, 2017 to 2026). A malignant neoplasm originating from the surface ovarian epithelium. "Studies in ovarian cancer have shown that FOXK1 is overexpressed and positively associated with poorer patient prognosis." (PMID 37174744, 2023). "High Aurora-A (log-rank P = 0.0007), SOX8 (log-rank P <0.0001), and FOXK1 (log-rank P = 0.0050) levels were associated with poor OS in chemosensitive ovarian cancer." (PMID 32550913, 2020). "Moreover, high FOXK1 expression was associated with poor survival in ovarian cancer patients." (PMID 32550913, 2020). "Similar results have been obtained in ovarian cancer models in which FOXK1 overexpression induced invasion and migration, indirectly increased the expression of MMP-9, and directly repressed the expression of p21." (PMID 37174744, 2023). "Aurora-A, a member of the Aurora kinase family, regulates glucose metabolism in ovarian cancer via the SOX8/FOXK1 signaling axis and induces cisplatin resistance." (PMID 34496868, 2021). "Here, we showed that FOXK1 inhibits cellular senescence and promotes glycolysis and chemoresistance in ovarian cancer through regulating cell senescence- and glycolysis-associated proteins, such as P16, hTERT, HK2 and LDHA." (PMID 32550913, 2020). "In summary, the Aurora-A/SOX8/FOXK1 signaling axis promotes chemoresistance via suppression of cell senescence and induction of glucose metabolism in ovarian cancer organoids and cells." (PMID 32550913, 2020). "To determine the clinical significance of Aurora-A, SOX8, and FOXK1 in ovarian cancer, we assessed their expression patterns using cisplatin-sensitive and -resistant ovarian cancer tissue microarrays (n = 246 and 185, respectively)." (PMID 32550913, 2020). "We observed "high" expression of FOXK1 in 70.81% (131/185) chemoresistant ovarian cancer tissues and 50.81% (125/246) chemosensitive tissues." (PMID 32550913, 2020). "Our results showed that SOX8 targets FOXK1, thereby regulating its transcription, which has significant impacts on senescence, glycolysis and chemoresistance in ovarian cancer." (PMID 32550913, 2020). "Here, our work demonstrates that FOXK1 is significantly high expression in ovarian cancer tissues and cell lines." (PMID 29050292, 2017). "The results of qRT-PCR and western blotting indicated FOXK1 was high expression in ovarian cancer cell lines, SKOV3 and OVCA429, compared with that in IOSE80 cells." (PMID 29050292, 2017). "In conclusion, our work indicate FOXK1 plays a key function in the ovarian cancer, it promotes cell proliferation and metastasis." (PMID 29050292, 2017). "Together, our study explain the function of FOXK1 in ovarian cancer and indicated that FOXK1 plays an essential function in mediating ovarian caner progression, and serves as a therapeutic target for ovarian cancer." (PMID 29050292, 2017). "To analyze the function of FOXK1 in ovarian cancer, we first detected the expression of FOXK1 in different ovarian cancer cell lines, SKOV3 and OVCA429, human normal ovarian cell lines IOSE80 was used as a control group." (PMID 29050292, 2017). "In order to investigate the function of FOXK1 in ovarian cancer, we overexpressed or knocked down FOXK1 in SKOV3 or OVCA429 cells, respectively." (PMID 29050292, 2017). "Consistently, our works have shown that FOXK1 promoted cell proliferation and invasion in ovarian cancer." (PMID 29050292, 2017). "Our work firstly find the effect of FOXK1 on cell proliferation and metastasis in the ovarian cancer, and explain the molecular mechanism of FOXK1 in cell proliferation." (PMID 29050292, 2017). "In our work, FOXK1 was found to up-regulate in ovarian cancer tissue samples and cell lines; moreover, the expression of FOXK1 was correlated with tumor size, metastasis and poorly prognosis." (PMID 29050292, 2017). "In conclusion, our work firstly find that FOXK1 is up-regulated in ovarian cancer tissues and cells." (PMID 29050292, 2017).
ovarian carcinoma (continued). "Additionally, a former study clarifies that FOXK1 is available to motivate chemoresistance via facilitating glycolysis in ovarian cancer." (PMID 35220908, 2022). "A recent study showed that Aurora-A mediates glucose metabolism via SOX8/FOXK1 in ovarian cancer." (PMID 33867847, 2021). "Similarly, high Aurora-A, SOX8, and FOXK1 expression was correlated with poor OS in chemoresistant ovarian cancer (P = 0.0035, 0.0001, and 0.0003, respectively)." (PMID 32550913, 2020). "Moreover, we found high expression of FOXK1 was correlated with multiple clinic pathologic in ovarian cancer, including tumor size, pathological stage and metastasis." (PMID 29050292, 2017). "In addition, survival curve analysis demonstrated a dramatically worse overall survival for ovarian cancer patients who had high expression of FOXK1, indicating that expression of FOXK1 was correlated with poor prognosis in ovarian cancer." (PMID 29050292, 2017). "Because of the correlation between the expression of FOXK1 and tumor size, we assumed whether FOXK1 promoted ovarian cancer cells proliferation." (PMID 29050292, 2017). "In addition, wound healing assay and transwell invasion analysis demonstrated that FOXK1 promoted migration and invasion in ovarian cancer." (PMID 29050292, 2017). "We found FOXK1 was high expression in cancer tissues, meanwhile, FOXK1 was up-regulated in ovarian cancer cell lines, so FOXK1 might act as an oncogene." (PMID 29050292, 2017). "FOXK1 serves as a novel molecular therapy target in ovarian cancer." (PMID 29050292, 2017). "In conclusion, FOXK1 facilitates ovarian cancer cell proliferation." (PMID 29050292, 2017). "Moreover, Aurora-A appears to exert a regulatory role through direct binding and phosphorylation of the transcription factor SOX8 to activate the SOX8/FOXK1 signaling axis, highlighting this pathway as a novel potential therapeutic target for chemoresistant ovarian cancer." (PMID 32550913, 2020). "In conclusion, we hypothesize that FOXK1 plays an important function in ovarian cancer." (PMID 29050292, 2017). "Moreover, high expression of FOXK1 predicts poor prognosis in ovarian cancer patients." (PMID 29050292, 2017). "Interestingly, we found that FOXK1 was up-regulated in ovarian cancer samples." (PMID 29050292, 2017). "Furthermore, we analyzed the relationship between FOXK1 and survival curve in ovarian cancer." (PMID 29050292, 2017). "So we assumed that FOXK1 might promote metastasis through regulation of EMT in ovarian cancer." (PMID 29050292, 2017). "FOXK1, a tumor promoter gene, is highly expressed in all types of cancers, like NSCLC, breast cancer, liver cancer, and ovarian cancer, etc." (PMID 35220908, 2022). "However, the function of FOXK1 in ovarian cancer remains unknown." (PMID 29050292, 2017). "However, the role of FOXK1 in ovarian cancer is still unknown." (PMID 29050292, 2017). "To evaluate the function of FOXK1 in ovarian cancer, we performed colony formation analysis, CCK-8 assay and cell cycle analysis to determine the effect of FOXK1 on cell proliferation and cell cycle." (PMID 29050292, 2017). "In ovarian cancer, elevated expression of the ‘oncogenic gene set’ comprising IGF2BP1, SRF, FOXK1 and PDLIM7 was not significantly (P = 0.077) associated with poor overall survival (OS) but showed the expected trend with a HR of 1.22." (PMID 30371874, 2019). "However, the expression patterns and roles of FOXK1 in ovarian cancer have not been established to date." (PMID 32550913, 2020).
hepatocellular carcinoma (12 papers, 2016 to 2025). A malignant tumor that arises from hepatocytes. "CHEK1, CDC25A, and CCNE1, together with CCND1, CCND3, CDK4, CDK6, BTRC, E2F3, and FOXK1, were previously identified as the targets of miR‐497∼195 cluster in hepatocellular carcinoma." (PMID 40548926, 2025). "Inhibition of the Akt/mTOR pathway by FOXK1 reduces cell viability and glycolysis in hepatocellular carcinoma cells." (PMID 39764438, 2024). "Studies have shown that FoxK1 was upregulated in hepatocellular carcinoma cells compared to normal liver cells." (PMID 35903069, 2022). "Circ_PRKCI targets miR-1294 and miR-186-5p by downregulating forkhead box K1 (FOXK1) expression to suppress glycolysis in hepatocellular carcinoma." (PMID 34829818, 2021). "FOXK1 is an important transcription factor of aerobic glycolysis, which is closely associated with tumorigenesis, including triple negative breast cancer, gallbladder cancer, hepatocellular carcinoma, and ovarian malignancy." (PMID 38383406, 2024). "In the present study, we explored the roles and interactions of oncogenic lncRNA small nucleolar RNA host gene 1 (SNHG1), miR-376, forkhead box protein K1 (FOXK1), and Snail in hepatocellular carcinoma (HCC)." (PMID 34095464, 2021). "For example, the inhibition of FOXK1 expression in hepatocellular carcinoma cells reduces cellular aerobic glycolysis and cell viability by impeding the transduction of the AKT/mTOR signaling pathway, a function distinct from that of Foxk1/2 in normal liver cells." (PMID 39749015, 2024). "In hepatocellular carcinoma (HCC), miR-186-5p interacted with long non-coding RNA 665 (LINC00665) and circular RNA protein kinase C iota (circ-PRKCI) to inhibit cellular viability and tumor progression by regulating Forkhead Box K1 (FOXK1) expression." (PMID 37841425, 2023). "Moreover, FOXK2, one of the two members of FOXK family, which collaborated with FOXK1 and showed the similar capability in a few physiological and pathological processes, has been demonstrated to change the phosphorylated status of AKT and exert oncogenic function in hepatocellular carcinoma." (PMID 32363163, 2020).
liver cancer (9 papers, 2019 to 2024). An epithelial or non-epithelial malignant neoplasm that arises from the liver. "Other studies have also demonstrated that downregulation of Forkhead box protein K1 (FOXK1) regulates aerobic glycolysis, thereby inhibiting liver cancer cell proliferation." (PMID 36297369, 2022). "It is reported that FOXK1 level was higher in liver cancer cells than in normal human hepatic cell line, FOXK1 silencing was found to repress cell viability." (PMID 31830901, 2019). "Furthermore, FOXK1 knockdown repressed liver cancer cell viability through mediating glycolysis, which was achieved by inhibition of the Akt/mammalian target of rapamycin pathway." (PMID 34095464, 2021). "Another study showed that FOXK1 knockdown inhibit glycolysis in liver cancer." (PMID 32363163, 2020).
lung cancer (9 papers, 2019 to 2022). A malignant neoplasm involving the lung. "It has been reported that miR-195-5p modulates the expression of forkhead box K1 (FOXK1), thereby inhibiting the proliferation of lung cancer cells." (PMID 35600383, 2022). "In lung cancer, FOXK1 acts as a downstream target of circMAN2B2/miR-1275 and plays a role as an oncogene." (PMID 30744670, 2019). "Furthermore, cirkMAN2B2 promotes the expression of FOXK1 by sponging miR-1275, thereby exerting a carcinogenic effect in lung cancer." (PMID 35342419, 2022).
breast carcinoma (8 papers, 2019 to 2025). "In breast cancer, the transcription factor FOXK1 serves as a crucial hub connecting metabolic disorders to the core clock machinery in cancer cells." (PMID 41143275, 2025). "In breast cancer, FoxK1 has both stimulatory and inhibitory effects, while FoxK2 has inhibitory effects." (PMID 35903069, 2022). "The average expression of Foxk1 gene has been reported to be lower in breast cancer tissues than in its adjacent tissues, and patients with low FoxK1 expression have a worse prognosis effect than with high expression." (PMID 35903069, 2022). "Further bioinformatic analysis from the Breast Cancer Gene-Expression Miner (bc-GenExMiner v4.3) showed that FOXK1 predicted a poorer metastasis-free survival in patients with basal-like breast cancer, which was consistent with our results." (PMID 32138762, 2020). "Nuclear FOXK1 then recruits corepressor complexes to specifically bind and silence core clock genes, including Clock, Per2, and Cry2, leading to uncontrolled cell proliferation and driving the malignant progression of breast cancer." (PMID 41143275, 2025). "Endothelial tube formation assays indicated that Foxk1 might regulate breast cancer angiogenesis through transcriptional repression of vascular endothelial growth factor." (PMID 35903069, 2022). "However, FoxK1 inhibits the EMT process by suppressing the expression of its target gene Twis (inducer of EMT) in breast cancer cell line McF-7." (PMID 35903069, 2022). "However, other studies concluded conversely that FoxK1 expression was significantly higher in breast cancer tissues than in adjacent tissues through QRT-PCR detection." (PMID 35903069, 2022). "Further mechanistic study revealed that HUMT expression was regulated in an epigenetic way, and it recruited the YBX1 protein to form the transcription complex on the FOXK1 promoter region and enhanced its transcription, resulting in breast cancer proliferation and lymph node metastasis." (PMID 32138762, 2020). "However, FOXK1 works as a tumor suppressor in breast cancer, and its expression was positively correlated with the prognosis of breast cancer." (PMID 30744670, 2019).
glioma (8 papers, 2019 to 2025). A benign or malignant brain and spinal cord tumor that arises from glial cells (astrocytes, oligodendrocytes, ependymal cells). "The function of ZRANB2/SNHG20/FOXK1 axis in glioma associated with vasculogenic mimicry formation was analyzed." (PMID 30744670, 2019). "We also queried the Cancer Genome Atlas database (TCGA), evaluated the association between FOXK1 and glioma, and drew the corresponding survival curve." (PMID 30744670, 2019). "It has been reported that the ZRANB2/SNHG20/FOXK1 axis plays a crucial role in regulating VM formation in the U87 and U251 glioma cell lines." (PMID 40277941, 2025). "FOXK1 expression negatively correlates with the pathological grade of glioma and negatively regulates the expression of VM-related molecules MMP1, MMP9, and VE-cadherin." (PMID 40277941, 2025). "SNHG20, which is stabilized by zinc finger RANBP2-type containing 2 (ZRANB2), maintains the stability of forkhead box K1 (FOXK1) mRNA to accelerate glioma progression." (PMID 38886753, 2024). "In glioma, FOXK1 overexpression promoted proliferation through the upregulation of cyclin D, c-myc, and β-catenin; promoted progression into S-phase; and reduced apoptosis." (PMID 37174744, 2023). "RBP-ZRANB2 is overexpressed in glioma cells, knockdown of ZRANB2 inhibits the ability of VM formation in glioma cells through SNHG20/FOXK1 pathway." (PMID 33542193, 2021). "The expression of ZRANB2, SNHG20 and FOXK1 in glioma were detected by real-time PCR or western blot." (PMID 30744670, 2019). "Our study finds that FOXK1 is down-regulated in glioma tissues and cells and is negatively correlated with pathological grade of glioma." (PMID 30744670, 2019). "The expression of FOXK1 in glioma tissues was down-regulated compared with NBTs and was negatively correlated with pathological grade of glioma." (PMID 30744670, 2019). "In consideration of the different reports of FOXK1 as an oncogene or tumor suppressor in different tumors, we refer to the TCGA database for FOXK1 expression in glioma, as well as survival curves." (PMID 30744670, 2019). "This study first examined the endogenous expression of ZRANB2, SNHG20 and FOXK1 in glioma tissues and U87 and U251 glioma cells, and studied the effects of ZRANB2, SNHG20 and FOXK1 on VM formation in glioma." (PMID 30744670, 2019). "Overexpression of FOXK1 significantly inhibits the proliferation, migration and invasion of glioma cells." (PMID 30744670, 2019). "Compared with the NBTs, the expression of FOXK1 was down-regulated in the glioma group, but there were only 5 cases in the NBTs group and the statistical difference was not so significant (P = 0.1069)." (PMID 30744670, 2019). "However, survival curve analysis shows that glioma cases of FOXK1 high-expression have longer survival than that with FOXK1 low-expression (P < 0.0001)." (PMID 30744670, 2019). "The expression of FOXK1 in glioma tissues as well as U87 and U251 was detected by western blotting." (PMID 30744670, 2019). "ZRANB2/SNHG20/FOXK1 axis plays an important role in regulating vasculogenic mimicry formation of glioma, which might provide new targets of glioma therapy." (PMID 30744670, 2019). "Moreover, FOXK1 level was elevated in glioma tissue samples and cell lines, and FOXK1 was identified to enhance cell growth in glioma." (PMID 31830901, 2019). "However, glioma with high FOXK1 expression had significant longer survival time than those with low FOXK1 expression (P < 0.0001)." (PMID 30744670, 2019). "In addition, transfection with FOXK1(−) could rescue the inhibitory effect of SNHG20(−) on proliferation, migration, invasion and VM of glioma cells, while FOXK1(+) could rescue the promoting effect of SNHG20 (+) similarly." (PMID 30744670, 2019). "At present, the regulation of VM in glioma by FOXK1 is unknown." (PMID 30744670, 2019).
glioma (continued). "ZRANB2 was also overexpressed in glioma cells and tissue, being a part of the ZRANB2/SNHG20/FOXK1 axis which was essential in regulating the vasculogenic mimicry formation of glioma." (PMID 34482648, 2021). "FOXK1 significantly reduces VM-related molecules MMP1, MMP9 and VE-Cadherin and reduced VM in glioma cells." (PMID 30744670, 2019). "FOXK1 inhibits transcription by binding to the promoters of MMP1, MMP9 and VE-Cadherin and inhibits vasculogenic mimicry formation of glioma cells." (PMID 30744670, 2019). "Co-transfection of SNHG20(−) cells with FOXK1(+) strongly decreased the expression of MMP1, MMP9, VE-Cadherin and strongly inhibited the abilities of proliferation, migration, invasion and VM of glioma cells." (PMID 30744670, 2019). "This study demonstrated that the ZRANB2/SNHG20/FOXK1 axis played an important role in regulating the expression of VM-related molecules MMP1, MMP9 and VE-Cadherin, and regulated the VM formation of glioma." (PMID 30744670, 2019). "FOXK1 down-regulates the levels of VM-related molecular MMP1, MMP9, VE-Cadherin by binding to their promoters and inhibited the VM formation in glioma cells." (PMID 30744670, 2019). "This study demonstrates for the first time that SNHG20 promotes the degradation of FOXK1 mRNA through the SMD pathway and regulates the VM formation in gliomas." (PMID 30744670, 2019). "FOXK1 inhibited transcription by binding to the promoters of MMP1, MMP9 and VE-Cadherin and inhibited the proliferation and migration, invasion and VM formation of glioma cells." (PMID 30744670, 2019). "There has been no report whether FOXK1 regulates transcription of MMP1, MMP9 and VE-Cadherin and regulates the VM formation in glioma." (PMID 30744670, 2019).